ERBB2 (erb-b2 receptor tyrosine kinase 2)
Diseases named in the same sentence as ERBB2 in open-access papers (continued):
Sharing a sentence is not in itself a finding about the gene and the disease.
esophageal adenocarcinoma (95 papers, 2010 to 2026). A malignant tumor with glandular differentiation arising predominantly from Barrett mucosa in the lower third of the esophagus. "Amplification of ERBB2, the gene encoding for HER2 (also known as HER2/neu), or HER2 overexpression is present in approximately 30% of esophageal adenocarcinomas." (PMID 35836094, 2023). "Lastly, esophageal adenocarcinoma patient with ERBB2 mutation (P597H) received afatinib, which targets ERBB2, but showed PD within 1 month." (PMID 27105424, 2016). "In 2021, Chen and colleagues reported the use of two heptapeptides (Cy5-labeled QRHKPRE, EGFR-specific, and IRDye800-labeled KSPNPRF, ErbB2-specific) given simultaneously during FME to visualize Barrett’s esophagus (NCT03589443)." (PMID 39513952, 2025). "Recent investigations demonstrated that amplification of ERBB2 (also called HER2) oncogenic form was found in esophageal adenocarcinoma progression, leading to a worse outcome for EAC." (PMID 32903213, 2020). "We generated lapatinib-resistant (LR) subclones from an initially lapatinib-sensitive ERBB2-amplified esophageal adenocarcinoma cell line, OE19." (PMID 25350844, 2014). "From the originally lapatinib-sensitive ERBB2-amplified esophageal adenocarcinoma cell, OE19, we generated several resistant subclones by prolonged exposure to lapatinib." (PMID 25350844, 2014). "Among several genetic abnormalities, both KRAS and ERBB2 amplification have been indicated as early events in adenocarcinoma development of Barrett's Esophagus." (PMID 22014070, 2011). "An esophageal adenocarcinoma patient with an ERBB2 mutation (P597H) also did not benefit from afatinib." (PMID 27105424, 2016). "As an effort to model acquired resistance of ERBB2-amplified GE adenocarcinomas to ERBB2 inhibition, we generated lapatinib-resistant subclones from an initially lapatinib-sensitive ERBB2-amplified esophageal adenocarcinoma cell line by prolonged exposure to the inhibitor." (PMID 25350844, 2014). "In the later stages of dysplasia and esophageal adenocarcinoma, significant amplification of oncogenes, including ERBB2 (HER2) results in the overexpression of HER2." (PMID 41537121, 2025). "The human epidermal growth factor receptor 2 (HER2, also known as ERBB2) is a commonly over-expressed oncoprotein in oesophageal adenocarcinoma (OAC)." (PMID 40473905, 2025). "We could recently show that GLI1 is activated via ERBB2 and PI3K/AKT/mTOR in esophageal adenocarcinoma in a SMO-independent manner." (PMID 28418873, 2017). "Our observation that the survival probability of ERBB2 positive patients (when their surviving time is longer than 2 years) was longer than that of ERBB2 negative patients in our GCA cohort, probably also reflects the similarity between esophageal adenocarcinoma features and GCA." (PMID 34764264, 2021). "Nevertheless, the TBR of these tracers was less than 1.4 for NDBE and LGD and was less than 1.7 for both heptapeptides in HGD and esophageal adenocarcinoma, suggesting that targeting EGFR and ErbB2 may not provide optimal dysplasia or esophageal adenocarcinoma detection." (PMID 39513952, 2025).
heart failure (93 papers, 2008 to 2026). Inability of the heart to pump blood at an adequate rate to meet tissue metabolic requirements. "Our finding that low circulating ERBB3 protein is associated with LV dysfunction and heart failure is further supported by data from patients receiving cancer therapeutics targeting ERBB2." (PMID 39180332, 2024). "The development of dilated cardiomyopathy in ErbB2-deficient mice and anti-HER2 (ErbB2)-targeted therapy patients suggests that the NRG-1/ErbB signaling pathway is implicated in the pathophysiology of heart failure." (PMID 38132657, 2023). "ERBB2, associated with heart failure, can improve mammalian heart regeneration, and promote cardiomyocyte dedifferentiation and proliferation." (PMID 34276800, 2021). "Cardiac myocytes of the heart express ErbB2/4 receptor tyrosine kinases and neuregulin treatment is associated with several advantageous responses which support its use in human patients with heart failure." (PMID 23776695, 2013). "Mostly based on the analogy between ErbB2 knockout-induced cardiomyopathy and trastuzumab-induced heart failure, many studies have concluded that trastuzumab causes heart failure by blocking the physiological actions of ErbB2 in the heart." (PMID 22482055, 2012). "Notably, mouse studies identified that cardiomyocyte specific loss of NRG3 receptors (ErbB2 and ErbB4) results in spontaneous heart failure suggesting a potential role for NRG3 in regulating cardiac homeostasis." (PMID 35959412, 2022). "Based on the indispensable role of NRG-1/ErbB system in the heart and the analogy between ErbB2 knockout-induced cardiomyopathy and trastuzumab-induced heart failure, many have concluded that trastuzumab causes cardiotoxicity by blocking the physiological actions of ErbB2 in the heart." (PMID 23202898, 2012). "We suggest that some patients with various stages of cardiac hypertrophy, including sub-clinical stages of disease, have dependence on ErbB2 to maintain cardiac function, and loss of ErbB2 activity (which can occur as a result of cancer therapy) results in heart failure." (PMID 22912742, 2012). "Breast cancer therapy with trastuzumab, an anti-ErbB2 monoclonal antibody, was shown to induce dilated cardiomyopathy and heart failure, pointing to a role of NRG-1 signaling in cardiac remodeling." (PMID 37965580, 2023). "In the context of heart failure ErbB2 and ErbB4 receptors are downregulated, indicating a compensatory attempt to preserve myocardial contractile performance." (PMID 37965580, 2023). "ErbB2 conditional deletion models develop heart failure and isolated cardiomyocytes from these mice are more sensitive to doxo." (PMID 31052420, 2019). "The combined role of ErbB2 in malignant tumor growth, and in compensatory processes in the heart, positions ErbB2 at the crossing between cancer and heart failure." (PMID 27596216, 2016). "Smart drug design developed in a stepwise fashion has now provided at least seven different anti-ErbB2 cancer drugs, together with a few molecules to activate physiological ErbB2 signaling for the treatment of heart failure." (PMID 27596216, 2016). "Growing knowledge of ErbB2 signaling as well as smart drug design has gradually led to the development of therapeutics to target ErbB2 signaling in the right cell type, for safe use in cancer and heart failure." (PMID 27596216, 2016). "The crucial position of ErbB2 at the cross road between cancer and heart failure has made it an attractive therapeutic target in both oncology and cardiology." (PMID 27596216, 2016). "In various experimental models of heart failure in animals, ErbB2 pathway is activated in early stages of heart failure but subsequently becomes inactivated in later stages of heart failure." (PMID 22912742, 2012). "In heart failure, the down-regulation of ErbB2 and ErbB4 receptors has also been correlated with decreased bcl-xL/xS ratios." (PMID 22912742, 2012).
heart failure (continued). "Decline in ErbB2 protein expression temporally correlating with transition to heart failure is also seen in animal models." (PMID 22912742, 2012). "For example, an inverse relationship of ErbB2 and miR7 was found in humans with dilated cardiomyopathy in a setting where ErbB2 appears to have an important role in cardiomyocytes of humans approaching heart failure." (PMID 22912742, 2012). "In humans, ErbB2 protein was shown to increase early in the development of the heart failure from multiple etiologies, while ErbB2 protein decreases in patients with terminal heart failure." (PMID 22912742, 2012). "We will address the biology of ErbB signaling in cancer and cardiac cells, the regulatory aspects and clinical benefits of NRG-1/ErbB signaling activation in heart failure, and the working mechanisms of different anti-ErbB2 drugs and their degree of cardiotoxicity." (PMID 27596216, 2016). "Accordingly, ErbB2-targeted inhibitory therapy of cancer may lead to ventricular dysfunction, and activation of ErbB2 for heart failure therapy may induce malignancy." (PMID 27596216, 2016). "Since there is no data in the literature in this field obtained from dogs, we could only speculate that the regulation of ErbB2 signalling pathway in dogs with ISACHC 3 heart failure could be the feature of end-stage heart failure also in this species." (PMID 24952741, 2014). "The synergistic increase of heart failure incidence has been related to the fact that ErbB2 expression is upregulated following doxorubicin administration, while trastuzumab inhibits the ErbB2 downstream pathways, which is essential for cell repair, survival, and function." (PMID 22482055, 2012). "Clues to the down-regulation of ErbB2 in terminal heart failure may be related to mechanisms involving miRNA." (PMID 22912742, 2012). "Hence, pharmacological inhibition of ErbB2 to treat cancer may induce heart failure, while systemic activation of ErbB2 to treat heart failure may induce malignancy." (PMID 27596216, 2016). "Activation of ErbB2/4 receptor tyrosine kinases in cardiomyocytes by neuregulin treatment is associated with improvement in cardiac function, supporting its use in human patients with heart failure despite the lack of a specific mechanism." (PMID 23776695, 2013). "Concerning the comparison of AKT- and ErbB2-over-expressing mice, activation of survival pathways by ErbB2 aside of PI3K/AKT pathway, such as HSPs and bcl-2 family proteins, may contribute to a sustained survival of ErbB2 transgenic mice versus AKT transgenic mice with resulting heart failure." (PMID 22912742, 2012). "One example that can be highlighted from our results is the presence of trastuzumab, an ERBB2 (MIM: 164870) inhibitor, as a potential repurposing opportunity for both atrial fibrillation and heart failure." (PMID 41376171, 2026). "However, in a pivotal trial involving ErbB-2-positive metastatic breast cancer patients treated with trastuzumab, 27% of patients exhibited some degree of cardiac impairment, including an asymptomatic decrease in left ventricular systolic function, and symptomatic heart failure in 19% of patients." (PMID 40612676, 2025). "For both groups of the study, the ERBB2 status of the cohort, chemotherapy regimen, and LVEF and/or heart failure assessment and incidence are summarized." (PMID 41206886, 2025). "We found similar, although less robust, patterns for both ERBB2 and ERBB4, with participants in the lowest quartile having higher risks of incident heart failure and cardiovascular mortality than some other quartiles when adjusted for age, sex, BMI, and DM." (PMID 39180332, 2024). "Proteins ErbB2 and ErbB4, downstream of NRG-1, have demonstrated mitigation of heart failure and, when activated to heterodimerize, trigger MAPK signaling." (PMID 37856516, 2023).
heart failure (continued). "RNA‐sequencing analysis of human heart samples with doxorubicin‐induced end‐stage heart failure and healthy controls showed that YAP and ERBB2 (HER2) as upstream regulators of differentially expressed genes correlated with doxorubicin treatment." (PMID 34931757, 2022). "Thus, it must be feasible to design drugs that specifically target either physiological or malignant ErbB2 signaling, to activate ErbB2 signaling in heart failure with no increased risk for cancer, and to inhibit ErbB2 signaling in cancer with no increased risk for heart failure." (PMID 27596216, 2016). "ERBB2 (score 8) and ERBB4 (score 7), both Neuregulin-1 receptors, are involved in cardiac regeneration after injury, and Neuregulin-1 itself is a therapeutic target for heart failure." (PMID 40791945, 2025). "By blocking ERBB2, these therapies interfere with NRG1-mediated protective and regenerative pathways, which can lead to impaired cardiac contractility, reduced stress resilience, and, in some cases, heart failure." (PMID 41011267, 2025). "The absence of ErbB1 gene in mouse models was associated with respiratory, gastrointestinal, and skin problems and the lack of ErbB2 gene in mouse models or the therapy against ErbB2 was accompanied by the heart failure." (PMID 28286519, 2017). "Since other models of hypertrophy lead to heart failure, our finding of a lack of heart failure in the ErbB2 mouse model is particularly remarkable." (PMID 22912742, 2012). "Remarkably, the hypertrophy induced by ErbB2 over-expression does not progress to overt heart failure." (PMID 22912742, 2012). "Previous studies and the work we present here, suggest that, although ErbB2 may drive hypertrophy in an attempt to improve heart function, ErbB2 expression is not maintained and heart failure ensues." (PMID 22912742, 2012). "In limited investigations into these pathways, ErbB2 mRNA was found to be increased following unloading in 36 patients with severe heart failure (NYHA class IV) due to ischemic and non-ischemic cardiomyopathy, but ErbB2 protein levels were not evaluated in this study." (PMID 22912742, 2012). "Remarkably, animals with ErbB2-induced cardiac hypertrophy do not develop heart failure." (PMID 22912742, 2012). "ErbB2 overexpression in the heart activates protective signaling pathways (PI3K, mTOR, and Bcl-2) and induces hypertrophy without heart failure." (PMID 31052420, 2019). "Both ErbB2 and IGF1R share downstream proteins that are pro-survival in nature, explaining why heart failure is not seen with over-expression of these proteins." (PMID 22912742, 2012).
inflammatory breast carcinoma (88 papers, 2007 to 2026). An advanced, invasive breast adenocarcinoma characterized by the presence of distinct changes in the overlying skin. "Inflammatory breast cancer (IBC) is characterized by NF‐κB activation, which causes endoplasmic reticulum (ER) downregulation, overexpression of EGFR and ErbB2, and hyperactivation of MAPK." (PMID 38077251, 2023). "The upregulation of PD-L1 in tumor cells has been identified in basal, ERBB2-enriched, and inflammatory breast cancers." (PMID 31146499, 2019). "Inflammatory breast cancer (IBC) is often characterized by overexpression of epidermal growth factor receptors 1 and/or 2 (ErbB1, ErbB2) that activate downstream survival pathways phosphatidylinositol-3-kinase (PI3K)/protein kinase B (AKT) and MAPK." (PMID 32656079, 2020). "Furthermore, PD-L1 overexpression is more prevalent in inflammatory breast cancers (a rare and particularly aggressive form of disease) that are ER (estrogen receptor) negative, basal, and ERBB2 enriched." (PMID 30021161, 2018).
lobular carcinoma (86 papers, 2005 to 2026). "Together with previous reports, our study shows that kinase domain (predominantly L755 site and V777L substation, especially in lobular carcinoma) is a hot spot for ERBB2 mutation in BC." (PMID 34257600, 2021). "Interestingly, a similar rate of ERBB2 mutations was previously reported in a smaller series by Lien and colleagues, who identified ERBB2 mutations in five out of 24 (21%) invasive and in-situ pleomorphic lobular carcinomas." (PMID 27602491, 2016). "ERBB2 amplification is a rare phenomenon in lobular breast carcinoma and sparse literature data point to poorer biological properties and unfavorable prognostic features." (PMID 38335502, 2024). "In conclusion, our study shows evidence that ERBB2‐amplified ILBC represents a distinct subgroup of lobular carcinomas with unfavorable prognostic characteristics and a distinct molecular genetic phenotype." (PMID 38335502, 2024). "Altogether 20 FFPE samples were subjected to FoundationOne®CDx testing: 10 patients with ERBB2‐amplified lobular carcinoma and 10 patients with ERBB2‐unamplified lobular carcinoma." (PMID 38335502, 2024). "Invasive lobular carcinomas also express the progesterone receptor (PR) at high rates (50%-70%), and less than 10% of these cells express HER2/ERBB2 (epidermal growth factor receptor 2)." (PMID 38665752, 2024). "One patient with lobular carcinoma had two CDH1 mutations and one ERBB2 mutation at ~16% allelic fraction, as well as a distinct set of mutations in PTEN, BRCA2 and PMS2 at ~5% allelic fraction." (PMID 24326041, 2013).
biliary tract cancer (83 papers, 2012 to 2025). "IDH1 mutations, FGFR2 fusions, MSI-H, NTRK fusions, BRAFV600E mutations and ERBB2 (HER2) have been classified as level I and three other aberrations as level III according to the most recent ESMO Guideline for Biliary Tract Cancer." (PMID 37711201, 2023). "In a cohort of 34 patients with biliary tract cancer, actionable variants were detected in IDH1/2 (18%), followed by FGFR1/2 (16%), EGFR or ERBB2/3 (16%), PTEN (14%), MDM2 (10%), and PIK3CA (10%)." (PMID 36290850, 2022). "ERBB2 amplifications are relatively rare in ICC compared with other types of biliary tract cancer (BTC)." (PMID 32631434, 2020). "We have also confirmed the high frequency of ERBB2 amplifications for 13% of patients with salivary gland carcinoma and 5.2% of patients with biliary tract cancers." (PMID 29515767, 2018). "Another recent study showed that the histone deacetylase inhibitor PCI-24781 potently inhibited the growth and induced apoptosis of biliary tract cancer cells by decreasing the expression and activity of erbB2." (PMID 26287365, 2015). "Interestingly, gemcitabine treatment is reported to elevate ERBB2 expression, making it a candidate target in breast, pancreatic, and biliary tract cancer treatment." (PMID 39509334, 2024). "The oncogene ERBB2, commonly known as HER2 (human epidermal growth factor receptor 2), is being evaluated as a precision medicine target in biliary tract cancer." (PMID 39198311, 2024). "Driver genes, such as the ERBB2, PIK3CA, IDH1/2, BRCA1/2, and FGFR2 fusion genes, have been identified in gallbladder and biliary tract cancers." (PMID 34573929, 2021). "In the same study, eight patients with biliary tract cancer overexpressing HER2 and three patients with ERBB2 structural abnormalities (D277Y, S310F, and A775-G776ins YVMA) were treated with pertuzumab plus trastuzumab, and the response rates were 37.5 and 33.3%, respectively." (PMID 33562094, 2021).
bone metastasis (83 papers, 2009 to 2026). Transfer of a neoplasm from its primary site to bones. "Taken together, all of these data inferred that the ERBB2 status, besides HR status, should be taken into account when talking about the risk of bone metastasis, as exemplified by triple negativity." (PMID 19778431, 2009). "In the present analysis, the triple negative phenotype brought about a dramatic increase in the hazard of developing bone metastasis with statistical significance compared with ERBB2+ subtype (P < 0.05)." (PMID 19778431, 2009). "In terms of bone metastasis, the hazard rate remained higher for the triple negative category than that for the ERBB2+ subtype." (PMID 19778431, 2009). "By incorporating EGFR, ERBB2, and ERBB3 expression in a decision tree model, four ERBB receptor status groups could be developed to segregate patients based on the risk of developing bone metastasis." (PMID 33918389, 2021). "Heterogeneous gene amplification was found both for the ERBB2 and the KRAS genes, but particularly enrichment of ERRB2 amplified cells was found in the biopsy from the bone metastasis after the initial three courses of chemotherapy." (PMID 22014070, 2011).